NDRG1 (N-myc downstream regulated 1)
Diseases named in the same sentence as NDRG1 in open-access papers (continued):
Sharing a sentence is not in itself a finding about the gene and the disease.
tumor (continued). "The increased expression of PKCδ in CRC tumor tissue could promote the invasion and migration of tumor cells, and one of the mechanisms may be regulating c-Myc to inhibit the expression of NDRG1 and promote EMT." (PMID 36816970, 2023). "Moreover, apoptolidin A effectively upregulated the suppressed expression of N-Myc downstream-regulated gene 1 (NDRG1), a tumor suppressor gene, in a concentration-dependent manner in CRC cells." (PMID 37111248, 2023). "It has been proposed that NDRG1 exhibits pleiotropic actions depending on the type of tumor." (PMID 37858101, 2023). "Furthermore, SGK1 phosphorylation of N-MYC downstream regulated gene 1 (NDRG1) promotes tumor cell growth and tissue extravasation." (PMID 37143725, 2023). "Given that TGFβ1 was found to activate GSK3β (p-GSK3β Tyr216) in MCF10A breast cells and human fibroblasts 36,37, we questioned whether staining of this active form in TNBC tumor tissue, could correlate with NDRG1 and p-NDRG1 staining." (PMID 36594086, 2023). "Similarly, tumor cell invasion in Matrigel-coated Boyden chambers was reduced by NDRG1 knockdown under TGFβ1 treatment only in MDA-MB-231, whereas no changes were detected in SUM159 cells." (PMID 36594086, 2023). "As mentioned, hypoxia in the tumor microenvironment stimulates NDRG1 expression in cancer cells." (PMID 37298315, 2023). "We constructed a novel putative model that suggests high expression of the key factor NDRG1 may contribute to macrophage polarization, infiltration into the tumor center, and ultimately lead to a poor prognosis." (PMID 38235128, 2023). "NDRG1 pleiotropy is driven by TGFβ to differentially promote metastasis and/or maintenance of CSCs at different stages of tumor progression, which could be abrogated by the inhibition of TGFβ and GSK3β." (PMID 36594086, 2023). "To clarify these contradictory results, we studied if NDRG1 and/or p-NDRG1 (Thr346) could be involved in tumor aggressiveness mediated by TGFβ1." (PMID 36594086, 2023). "Studies have shown that NDRG1 play important roles in tumor invasion and metastasis." (PMID 38097352, 2023). "In a word, we found that the increased expression of PKCδ in CRC tumor tissue could promote the invasion and migration of tumor cells, and one of the mechanisms may be regulating c-Myc to inhibit the expression of NDRG1 and promote EMT." (PMID 36816970, 2023). "NDRG1 is known to have both oncogenic and anti-tumor/anti-metastasis roles depending on the tumor type 30, but the reasons are still unknown." (PMID 36594086, 2023). "We have also identified that NDRG1 is downstream of TGFβ-induced GSK3β, and our results suggest that the role of NDRG1 in tumor promotion could be attributed to the modulation of NF-κB." (PMID 36594086, 2023). "Therefore, the oncogenic versus tumor suppressor roles of NDRG1 in different tissues should be interpreted considering the extensive number of NDRG1 counterparts in each situation." (PMID 37249826, 2023). "NDRG1 may promote tumor progression by affecting macrophage differentiation, as observed by pseudotime analysis, and is mostly involved in immune and oncogenic pathways." (PMID 38235128, 2023). "Through qRT-PCR analysis, we observed significantly elevated NDRG1 expression in tumor tissues." (PMID 38235128, 2023). "Additionally, several studies have confirmed that NDRG1 is highly expressed in macrophages within the tumor microenvironment." (PMID 38235128, 2023). "Similarly, in non-small cell carcinoma, NDRG1 silencing has attenuated tumor growth and reduced angiogenesis." (PMID 37249826, 2023). "NDRG1 affects oncogenic signaling pathways and tumor progression." (PMID 36793283, 2023). "Being confirmed that NDRG1, p-NDRG1 (Thr346) expression, and subcellular localization is associated with poorer survival of TNBC patients and that it is involved in tumor progression induced by TGFβ signaling, our final goal was to propose a potential way for their personalized treatment." (PMID 36594086, 2023).
tumor (continued). "According to our data set, three genes, EZH2, GRPEL2, and NDRG1, and one clinical factor, tumor size, could be used as reliable indicators for evaluating the prognosis in patients with HCC." (PMID 36686830, 2022). "In addition, the mRNA levels of N-Myc downstream regulated 1 (Ndrg1), a tumor metastasis suppressor, were elevated in the ID + AOM/DSS group, but not in the IOL + AOM/DSS group, compared with those in the IC + AOM/DSS group." (PMID 35631174, 2022). "Previously, NDRG1 has been reported interacting with GSK3b to promote tumor growth." (PMID 35563887, 2022). "Therefore, the upregulation of NDRG1 or downregulation of NDRG2 seemed to suppress tumor immunity, assist cancer cells to escape from immune elimination, and finally promote tumorigenesis." (PMID 35795037, 2022). "ID + AOM/DSS may hinder tumor development in the AOM/DSS model by inhibiting the PI3K/AKT pathway by increasing the expression of Ndrg1." (PMID 35631174, 2022). "Demographics and tumor characteristics based on the expression of NDRG1 and NDRG2." (PMID 35795037, 2022). "NDRG1-mediated inhibition of tumor growth and metastasis may explain the anti-cancer effects of iron chelating agents such as Dp44mT31,39,40." (PMID 36357486, 2022). "Additionally, NDRG1-high tumours showed reduced BrM relapse-free survival when compared to NDRG1-low tumours." (PMID 36497221, 2022). "This contradictory result may be tumor type-specific, further emphasizing that NDRG1 is involved in complex biological processes." (PMID 35795037, 2022). "Therefore, the current research results suggest that EZH2, GRPEL2, NDRG1, and tumor size are reliable prognostic indicators." (PMID 36686830, 2022). "The immunohistochemical images showed HJURP/YAP1/NDRG1 axis promotes TNBC tumor growth." (PMID 35459269, 2022). "Reports on the role of NDRG1 in modulating tumor development have been inconsistent." (PMID 35563887, 2022). "The product of the NDRG1 gene is a stress-responsive protein that acts as a tumor suppressor." (PMID 35682850, 2022). "Interestingly, a recent study showed that proneural marker ASCL1 maintained the proneural phenotype of tumor cells by inhibiting the expression of mesenchymal marker NDRG1." (PMID 36061208, 2022). "The NDRG1 promoter region consists of repeated CpG islands regions, which are often observed as sites of DNA methylation mediated gene regulation in cancers and tumour suppressor genes." (PMID 36497221, 2022). "The pleiotropy of NDRG1 may reflect the heterogeneity of signal transduction in different tumor cell-types." (PMID 35795037, 2022). "Further analysis of 8q24.2 showed that the amplification of two oncogenes, MYC and NDRG1, located on this fragment might be associated with HRD across tumor types." (PMID 34976815, 2021). "The NDRG1-induced increase of SMAD4 expression may also activate its other tumor suppressor effects, such as arresting the cell cycle at G1 (acting as a G1/S checkpoint) and inducing the expression of the cyclin-dependent kinase inhibitor, p21." (PMID 34572031, 2021). "It is possible that despite the capacity of NDRG1 to act as an oncogene, treating cells with iron chelators could return its tumour suppressive functions in certain conditions." (PMID 33520115, 2021). "M1-3 had similar human tumour marker expression but diverse oncogenic signalling activation patterns, with OSAhigh M1 and M3 showing distinctive signalling: M1 had low p-Akt and p-NDRG1 and high p-p38 and M3 had high PI3K/mTOR effectors and high p-ERK." (PMID 33790302, 2021). "Similarly, after treatment, the average tumor weight of the control group was significantly smaller than that of the NDRG1-knockdown group (196 ± 145 mg vs 573 ± 96 mg, p < 0.01)." (PMID 34385595, 2021). "This review hypothesizes that NDRG1 could inhibit the oncogenic function of c-Cbl, which may be another mechanism of its tumor-suppressive effects." (PMID 34572031, 2021).
tumor (continued). "Moreover, we generated in vivo mouse xenograft model and found that knockout of NDRG1 in CLDN2‐absence context resulted in bounce back of the subcutaneous tumour size from shrank." (PMID 34965023, 2021). "Reports of NDRG1 in modulating tumor development are inconsistent." (PMID 34307149, 2021). "HIF-1α alters the metabolism of tumor cells, causes the release of the proangiogenic factors vascular endothelial growth factor (VEGF), N-myc downstream regulated 1 (NDRG1) and Glucose transporter 1 (GLUT1), promotes cell proliferation and inhibits cell apoptosis." (PMID 32312328, 2020). "Taken together, we show that treatment with JR-AB2-011 impairs the mTORC2-specific targets Akt and NDRG1 and, therefore, may be a modulator of cancer cell survival, motility, and tumor progression." (PMID 33375117, 2020). "However, silencing of NDRG1 led to reduced proliferation and invasion capacity as well as tumor growth in vitro and in vivo in these studies." (PMID 33375117, 2020). "While the NDRG family shares a high sequence identity, their tissue distributions differ and they play different roles in tumor regulation: NDRG1 has been proposed as a prognostic biomarker for colorectal cancer because it was reported to suppress cell invasion, migration, and proliferation." (PMID 31935861, 2020). "Therefore, increased activity of the GC-GR pathway with enhanced induction of Sgk1 and NDRG1 in carcinoma cells play pivotal roles in tumor progression and development of chemo-resistance in patients with ESCC undergoing NAC." (PMID 32106831, 2020). "Univariate analysis showed that NDRG1 expression (hazard ratio (HR) = 2.1, p = 0.0150), tumor grade (HR = 2.4, p = 0.0463), disease stage (HR = 4.6, p = 0.0011), ER status (HR = 0.4, p = 0.0098), and adjuvant radiation therapy (HR = 0.5, p = 0.0434) were associated with OS." (PMID 33321961, 2020). "Besides, hsa_circ_0003159 decreased GC cell xenograft tumor growth by regulating miR-223-3p and NDRG1." (PMID 32099530, 2020). "Our data suggest further investigation of IGF-1R inhibitors in combination with MEK inhibition and dexamethasone, possibly in those patients whose tumor cells show amplification of IGF-1R or elevated expression of NDRG1, may be warranted." (PMID 32228485, 2020). "Previous studies have shown that NDRG1 is involved in tumour invasion and metastasis." (PMID 32025371, 2020). "Moreover, N-myc downstream regulated gene 1 (NDRG1) is demonstrated as a metastasis suppressor and inhibit tumor malignancy of GC." (PMID 32099530, 2020). "A study reported that NDRG1 overexpression may inhibit the expression of E-cadherin and enhance the expression of Snail, and consequently regulate tumour growth and metastasis in oesophageal squamous cell carcinoma." (PMID 32025371, 2020). "Along this line, higher expression of CaIX, Phd3, Slc7a5, Glut1, Pgm1 occurred but not Ndrg1 in a Vhl-deficient renal cell mouse model when compared with non-tumor renal region, which is in line with our data in Vhl-deficient kidneys." (PMID 33321829, 2020). "Additionally, the expression levels of hsa_circ_0003159, miR-223-3p and NDRG1 were detected in tumor tissues of each group." (PMID 32099530, 2020). "One of the important effectors of DpC and Dp44mT anti-tumor activity is NDRG1 expression." (PMID 33334021, 2020). "Additionally in a variety of adult cancer cell-types, the thiosemicarbazones demonstrated strong activity at up-regulating NDRG1 in all three pediatric tumor cell lines." (PMID 33334021, 2020). "To determine whether NDRG1 suppresses tumour progression in ccRCC, we analysed the interaction of NDRG1 with the genes downstream of VHL." (PMID 32537867, 2020). "All these results above indicated that p21 overexpression could attenuate the tumor growth induced by NDRG1 silencing." (PMID 31831018, 2019). "Therefore, NDRG1 is recognized as “tumor suppressor”, which can induce tumor differentiation, inhibit invasion, metastasis, and cell proliferation." (PMID 31831018, 2019).
tumor (continued). "Some studies reported that NDRG1 could promote HCC tumor growth, metastasis, and malignancy, while others showed that NDRG1 expression was lower in HCC tumor tissues than in normal tissues and inhibited tumor growth." (PMID 31831018, 2019). "Moreover, xenograft models proved that NDRG1 overexpression significantly suppressed tumor growth, while NDRG1 knockdown increased growth in vivo." (PMID 31831018, 2019). "N-myc downstream-regulated gene 1 (NDRG1) has been shown to play a key role in tumor metastasis." (PMID 31831018, 2019). "Recent studies have shown NDRG1 could induce cancer cell G0/G1 arrest, inhibiting tumor proliferation." (PMID 31831018, 2019). "Tumor volume is correlated with proliferative abilities of tumor, suggesting that NDRG1 may be capable of modulation of the proliferative abilities of tumor." (PMID 31831018, 2019). "In this study, we demonstrated that NDRG1 could inhibit tumor proliferation through increasing p21 protein expression in vivo and in vitro." (PMID 31831018, 2019). "In this study, we demonstrated that NDRG1 could inhibit tumor growth through increasing p21 protein expression." (PMID 31831018, 2019). "Both NDRG1 and p21 are tumor suppressors, combined with the results above, thus, we hypothesized that NDRG1 might inhibit tumor proliferation via up-regulating p21 expression." (PMID 31831018, 2019). "Previous studies showed that NDRG1 could be a tumour suppressor in colon, prostate and pancreatic cancer." (PMID 30914736, 2019). "The average tumor weight also showed similar trends: 192.4 ± 8.79 mg vs. 412.6 ± 11.24 mg (p < 0.0001) for NDRG1 and Vector group, 685.0 ± 14.4 mg vs. 386.2 ± 12.2 mg for SH-NDRG1 and sh-Control group." (PMID 31831018, 2019). "In PDAC, CXCL1 is described as being a part of the NDRG1/Cap43 regulated tumor suppressor pathway." (PMID 31561620, 2019). "In conclusion, our results demonstrated that NDRG1 could inhibit tumor growth in vivo and in vitro through increasing p21 protein expression by suppressing its ubiquitylation." (PMID 31831018, 2019). "The majority of proteins (ACTR2, CSTB, LTA4H, PGK1, NDRG1, FSCN1, ITGAV, THBS2) significantly associated with clinical parameters showed lower expression in the ITF of the tumor stroma or neoplastic islands, with the exception of COL6A1, COL1A2, S100A8, S110A9, and MB." (PMID 30185791, 2018). "In conclusion, our results suggest that NDRG1 may play an important role in mediating the anti-tumor activity of DpdtC in HER2-overexpressed cancer via selective suppression of the HER2-ERK1/2 pathway." (PMID 29467385, 2018). "Higher levels of human NDRG1 may act as a tumor suppressor that is involved in cellular differentiation, cell cycle regulation, responses to hormones, nickel and stress, cell adhesion and ECM degradation." (PMID 30185791, 2018). "Despite as the potent metastasis suppressor, how NDRG1 participates in the mechanism of dithiocarbamate-mediated tumor growth inhibition remains unclear." (PMID 29467385, 2018). "The results indicated that prioritized proteins, CSTB, NDRG1, PGK1, and ITGAV, may play a relevant biological role in tumor progression, since they were potentially associated, directly or indirectly, with patient prognosis." (PMID 30185791, 2018). "One tumor suppressor that has recently attracted increasing attention is NDRG1." (PMID 29137287, 2017). "We then asked whether treatment with LSD1 inhibitors and over-expression of NDRG1 might impair the migration and invasion of tumor NB cell lines." (PMID 27894074, 2017). "The protein N-myc down-regulated gene 1 (NDRG1) represses tumour metastasis." (PMID 28545025, 2017). "NDRG1 is also involved in other processes related to oncogenesis and tumour metastasis (reviewed)." (PMID 28545025, 2017). "Additionally, lower NDRG1 protein expression in the primary tumor predicts poor five‐year patient survival for all three tumor types." (PMID 28371345, 2017). "NDRG1 is a potent metastasis suppressor in multiple tumor-types." (PMID 28537875, 2017).
tumor (continued). "In this study, we confirmed that rGal3C could effectively induce decrease of NDRG1 in HepG2, suggested that rGal3C could play its anti-tumour role through down-regulation of NDRG1 in HCC." (PMID 28701735, 2017). "We therefore asked whether MNKs regulate NDRG1, a phosphoprotein that negatively affects cell migration and tumour metastasis." (PMID 28545025, 2017). "Our findings suggest that LSD1 pharmacological silencing might control EMT in NB tumor cell lines by upregulating NDRG1 expression." (PMID 27894074, 2017). "Moreover, our previous work revealed a significant inverse correlation of NDRG1 expression with tumor stage, differentiation status and metastasis in CRC patients, suggesting the clinical significance of NDRG1." (PMID 28537875, 2017). "Previously, we reported that N-myc downstream-regulated gene 1 (NDRG1) is strongly up-regulated under hypoxia and may play an important role in tumor adaptation to fluctuating oxygen concentrations." (PMID 26852918, 2016). "To examine whether NDRG1 knockdown affects tumor growth and angiogenesis, we compared tumor growth and angiogenesis between WT and Ndrg1 KO mice in a syngeneic mouse tumor model." (PMID 26778110, 2016). "We hypothesize that the mechanism by which deferasirox exerts its anti-tumor effects may involve NDRG1." (PMID 26965928, 2016). "NDRG1 has been shown to have numeral effects on cancer cells, such as pro-differentiation, cell cycle arrest, and metastasis attenuation, and, thus, been inferred as a tumor suppressor gene in OSCC cells." (PMID 27589737, 2016). "In addition, in the subcutaneous tumor mouse model, overexpression of NDRG1 in U-87 MG cells suppressed tumorigenicity in vivo." (PMID 25777142, 2015). "Based on the current study, an intriguing hypothesis was that down-regulation of c-Src by NDRG1 was also engaged in this anti-oncogenic effect of suppressing tumor cell migration." (PMID 25860930, 2015). "In addition to its effects on primary tumor growth, the role of NDRG1 as a metastasis suppressor has been demonstrated in vitro and in vivo." (PMID 26431493, 2015). "Moreover, NDRG1 is an iron-regulated gene that is markedly increased by cellular iron depletion using iron chelators known to have anti-tumor properties." (PMID 25213357, 2015). "Examining tumor volume over 30 days, our results showed that tumors derived from injecting 1 × 107 cells grew significantly (p < 0.001–0.05) slower in the NDRG1 over-expressing group than those in the NDRG1 Con and all other groups." (PMID 26418878, 2015). "We aim to further elucidate the biological functions mediated by NDRG1 in HCC cells, so as to improve our understanding of hepatocarcinogenesis and tumor progression, which in turn may allow rational design of novel therapeutic approaches targeting NDRG1." (PMID 26359353, 2015). "Interestingly, our previous studies demonstrated that NDRG1 substantially inhibited tumor cell migration by reducing ROCK/pMLC2 pathway activation, which concurs with the findings from the current investigation." (PMID 25860930, 2015). "Considering the inhibitory effect of NDRG1 expression on c-Src activation, it was important to examine whether NDRG1 could inhibit signaling targets downstream of c-Src to decrease tumor cell migration." (PMID 25860930, 2015). "NDRG1 has been demonstrated to inhibit primary tumor growth in vitro and in vivo." (PMID 26431493, 2015). "Importantly, these agents also up-regulate the growth and metastasis suppressor protein, NDRG1, which has been shown to be vital in the progression and outcome of a variety of neoplasms." (PMID 26431493, 2015). "Furthermore, in a subcutaneous mouse tumor model, NDRG1 overexpression significantly reduced subcutaneous tumor growth." (PMID 25777142, 2015). "We advocate that monitoring NDRG1 phosphorylation responses following administration of Akt inhibitors could represent an effective general biomarker to assess SGK1 activity in tumour cells." (PMID 23581296, 2013).